PIK3CA (phosphatidylinositol-4,5-bisphosphate 3-kinase catalytic subunit alpha)
Diseases named in the same sentence as PIK3CA in open-access papers (continued):
Sharing a sentence is not in itself a finding about the gene and the disease.
cancer (continued). "The treatment is specifically for those with a PIK3CA gene mutation, whose cancer has progressed while on or after receiving an aromatase inhibitor." (PMID 39086675, 2023). "Most PIK3CA mutations lead to a constitutive active PI3K pathway, but interestingly, the literature is inconsistent with regards to the impact of PIK3CA mutations on patient survival across many cancer types." (PMID 36943861, 2023). "Changes in the PI3K/AKT/mTOR pathway during cancer development are mainly due to mutations in PIK3CA and AKT, overexpression of RTKs or loss of PTEN." (PMID 37108109, 2023). "OS was extended by 7.9 months in patients with PIK3CA mutated cancer, establishing PIK3CA mutation as a predictive biomarker for alpelisib benefit." (PMID 37035239, 2023). "Phosphoinositide 3-kinase α (PIK3CA) is one of the most mutated genes across cancers, especially breast, gynecologic, and head and neck squamous cell carcinoma tumors." (PMID 37623743, 2023). "Recent work using next-generation sequencing (NGS) has demonstrated driver mutations in cancer associated genes such as PIK3CA, ARID1A, PPP2R1A and KRAS in both, ovarian endometrioma and DIE." (PMID 37005590, 2023). "Components of the PI3K-AKT-mTOR pathway are regularly mutated across cancer, with PIK3CA among the most frequently mutated genes." (PMID 37170094, 2023). "For example, the amplification of the HER2 gene can lead to the rapid growth and spread of cancer cells, and the expression of BRCA1, BRCA2, EGFR, and PIK3CA can also increase the proliferation and migration risk of cancer cells." (PMID 37960513, 2023). "Somatic activating mutations of PIK3CA are important cause of various human cancers, and several hotspot mutations, including p.E542K, p.E545K and p.H1047R/L, are most frequently found." (PMID 37658401, 2023). "Analyzing specific PIK3CA mutations related to cancer and mendelian overgrowth, we found support for the described sensitivity of H1047 mutants to GSK690693 targeting the AKT pathway." (PMID 36472769, 2023). "In conclusion, PIK3CA mutations are widely spread across all cancer types and represent a vast entity of different mutations." (PMID 36934165, 2023). "Combining with other oncogenes, activating PIK3CA mutations in transgenic mice were utilized to create various types of cancer mouse models (such as colon, prostate, lung, and brain cancers, etc.), in either a non-inducible or conditional and inducible system." (PMID 37109059, 2023). "A subset of PIK3CA-mutant cancers harbor multiple copies of mutant PIK3CA in cis (same allele) or trans (separate alleles) that additively affect downstream signaling and cellular phenotypes in a dose-dependent manner or elicit biphasic effects." (PMID 37471270, 2023). "The PI3K/AKT pathway can be abnormally triggered in a wide range of cancers due to a plethora of mechanisms including somatic mutations and germline mutations in PIK3CA, AKT, PTEN and mTOR genes." (PMID 36765661, 2023). "The MAPK pathway mutation is found in most cancers, and the PIK3CA/AKT pathway is known to be upregulated in thyroid cancer." (PMID 37932340, 2023). "Our results are consistent with what is described in literature, with a PIK3CA mutation being detected in over 10% of all cancer patients." (PMID 36934165, 2023). "Abnormalities in the PI3K/AKT/mTOR signaling pathway are very prevalent in malignant tumors and mutations in PIK3CA have been frequently detected in many cancers including OCCC, reportedly at 40%." (PMID 37270486, 2023). "Mutations in PIK3CA in adipose tissue can lead cells to acquire many characteristic changes of cancer cells, such as increased glucose uptake, enhanced Warburg effect activity, and increased synthesis of oncogenic macromolecules." (PMID 37719859, 2023).
cancer (continued). "The catalogue of somatic mutations in cancer (COSMIC) shows that 80% of PIK3CA mutations concern only three “hotspots” and are located on the kinase and helical domains of the catalytic subunits." (PMID 36900211, 2023). "As expected, we confirmed in our study that PIK3CA mutations are widely spread in different cancer locations." (PMID 36934165, 2023). "Amplification and/or somatic mutations within the alpha catalytic subunit of PI3K (PIK3CA) are present in many human cancers including cervical cancer." (PMID 36763589, 2023). "PIK3CA is frequently mutated also in cancer and other pathologies characterized by tissue hyperplasia, the so-called PIK3CA-related overgrowth spectrum." (PMID 36688917, 2023). "PIK3CA (phosphatidylinositol 3-kinase, catalytic, α-polypeptide), the gene encoding the p110α subunit, is frequently mutated in ~30% of common human cancers and has been studied most thoroughly." (PMID 36839989, 2023). "The most frequently mutated oncogene in these carcinomas in general is PIK3CA, which encodes for the catalytic subunit PI3K." (PMID 37240895, 2023). "Loss of tumor suppressor phosphatase and tensin homolog (PTEN) that dephosphorylates PIP3 into PIP2 and mutations in PIK3CA gene that encodes p110α subunit are commonly observed in multiple cancer types." (PMID 36676983, 2022). "PIK3CA mutations are frequently associated with other gene mutations which are involved in significant cancer-related pathways, such as the Wnt/beta-catenin pathway and tyrosine kinase receptors K-Ras/BRAF/MAPK." (PMID 35723313, 2022). "In cancers, a small number of studies have demonstrated a positive correlation between PIK3CA mutational status and upstream activation of the mTOR pathway." (PMID 35094709, 2022). "A striking majority of these diseases show the same hotspot, activating mutations in the PIK3CA gene as over one in eight United States cancers." (PMID 36353506, 2022). "Taken together, the sensitivity of PIK3CA-mutated cancers to aspirin has gained much attention, especially in recent years." (PMID 35780223, 2022). "The p110 α (p110α) subunit encoded by the PIK3CA gene is the most prevalent altered catalytic subunit of the phosphatidylinositol 3-kinase (PI3K) isoform in cancer." (PMID 35402264, 2022). "PIK3CA mutation is the most common gene mutation in cancer and is an independent risk factor for affecting the overall survival (OS) and progression‐free survival (PFS) in NSCLC patients." (PMID 35521981, 2022). "This approval highlights mutant PIK3CA (encoding p110α protein) as a critical cancer drug target and the importance of further understanding the molecular mechanisms by which PIK3CA mutations drive tumorigenesis." (PMID 35418124, 2022). "The PIK3CA gene encodes p110α protein, one of the catalytic subunits of the PI3K enzyme, playing a vital role in the pathogenesis of cancer driven by PIK3CA mutations, as well as in the development of resistance in breast cancer." (PMID 38089455, 2022). "An association of mutations in PIK3CA with mutations in MMR-related genes is also observed in these cancers." (PMID 35323317, 2022). "PIK3CA was one of the most commonly mutated genes across different cancer types, and this study also obtained consistent results with the published reports." (PMID 35242279, 2022). "Abnormal signaling through this pathway relates to several important aspects of cancer prognosis and treatment, including tumorigenesis, progression, and therapeutic resistance, which suggests prognostic relevance of PIK3CA mutations for patients with mBC." (PMID 36131248, 2022). "In contrast to the mutual exclusivity of mutations in oncogenes KRAS and BRAF, cancers with PIK3CA mutations have often concomitant mutations in either of these genes of the KRAS/BRAF/MEK/ERK pathway." (PMID 36295658, 2022). "Together, our data suggest that the p85β protein dissociates from the mutant p110α in cancer cells with a PIK3CA helical domain mutation." (PMID 35418124, 2022).
cancer (continued). "The presence of Kirsten RAS 2 viral oncogene homolog (KRAS) mutations associates with PIK3CA mutations in cancer." (PMID 36046843, 2022). "Somatic mutations in PIK3CA occur frequently in cancers other than LMs and other PIK3CA-related overgrowth spectrums." (PMID 35094709, 2022). "In all the four components, two pathogenic mutations, known to be recurrent hotspots in cancer, were present: PIK3CA c.3140A > T p.(His 1047Leu) and CTNNB1 c.94G > T p.(Asp32Tyr)." (PMID 34342838, 2022). "The mutations and amplification of PIK3CA are the most occurring events in cancer, and abnormal PI3K activity is a transforming event in the disease process." (PMID 35402264, 2022). "The most frequently mutated ICD-related genes at the pan-cancer level was PIK3CA (41%) with missense variation." (PMID 36497433, 2022). "Cancers that acquire a mutation/copy gain in PIK3CA or loss of PTEN have been implicated in enhanced sensitivity to inhibitors targeting the PI3K/AKT/mTOR pathway." (PMID 35918763, 2022). "Several cancers have demonstrated abnormal PI3Kα/Akt/mTOR signaling pathway activation, in which PIK3CA gene expression has been implicated." (PMID 36145724, 2022). "Compared with the DNA analysis of cancer tissue samples, the test results of therascreen PIK3CA RGQ PCR Kit and cobas®EGFR Mutation Test v2 have higher false negatives." (PMID 35735625, 2022). "Mutation of PIK3CA has been confirmed in various cancers, which is considered to serve as an oncogene." (PMID 36052751, 2022). "According to various studies, the mutation frequency of the PIK3CA gene ranges from 11% to 14% in cancer." (PMID 35402264, 2022). "By sequencing histologically normal endometrial glands, we and others have identified numerous somatic mutations in cancer-associated genes, such as PIK3CA and KRAS15–17." (PMID 35177608, 2022). "We have shown that the nuclear p85β stabilizes EZH1 and EZH2 in cancer cells with a PIK3CA E545K mutation." (PMID 35418124, 2022). "Here, we made use of two human organoid cancer models, HBCx4B and HBCx60, derived from two patient-derived xenograft triple-negative breast tumors that harbor PIK3CA mutations, E545K and H1047R, respectively." (PMID 35365185, 2022). "In cases with somatic ARID1A and/or PIK3CA mutations, they were consistently found to be present across all cancer specimens, as well as any AE or TE from those cases." (PMID 35457244, 2022). "The role of PIK3CA is to promote the catalytic reaction of the message transmission; and the mutation of PIK3CA will change the way of cells, regulating physiological responses to cause the formation of cancer." (PMID 35743172, 2022). "Activation of PI3K pathway is a frequent observed in hallmark of cancer, which is highlighted by the prevalence of somatic mutations or amplification of PIK3CA in HNSCC." (PMID 35546399, 2022). "Targeting phosphatidylinositol 3-kinase α is therefore an attractive strategy for treating cancers harboring PIK3CA mutations." (PMID 36385120, 2022). "The proportion of patients with PIK3CA mutations varied among 21 types of cancer, with the top being BRCA, CESC, SCL, and UCEC." (PMID 35778737, 2022). "In human cancers, PIK3CA is the commonly mutated gene which encodes the p110α catalytic subunit of the PI3K pathway, and was over-expressed in breast cancer." (PMID 35164019, 2022). "Next, we set out to elucidate the molecular mechanisms by which p85β promotes the growth of cancer cells with a PIK3CA helical domain mutation." (PMID 35418124, 2022). "Lastly, we focused on the LUSC driver gene with the largest APOBEC-mutation-driven cancer effect sizes, apart from PIK3CA." (PMID 35872531, 2022).
cancer (continued). "As controls, we measured the proportion of HLA-A LOH events involving HLA-A*03:01 versus the alternative HLA-A allele in cancers with PIK3CA (E542K) or PIK3CA (E545K)." (PMID 35484264, 2022). "In a meta-analysis of cancer genome sequencing results, PIK3CA and PTEN are highly mutated genes in most human cancers." (PMID 35465317, 2022). "In the genetic field, in particular, mutations that activate PIK3CA associated with the loss of ARID1A expression appear to be necessary for cancer development." (PMID 35328379, 2022). "The findings of this study provide valuable input for further research and targeted therapies for PIK3CA mutation-carrying cancer." (PMID 35778737, 2022). "We compared the PIK3CA mutation frequencies in different cancer types between the Chinese cohort and COSMIC database." (PMID 35778737, 2022). "In summary, this study characterized the genomic landscape of PIK3CA mutations in various cancers in a large Chinese population and analyzed concomitant genomic alterations/pathways in different cancer types." (PMID 35778737, 2022). "Different landmark studies suggest that the effect of aspirin on cancer is limited to patients with PIK3CA-mutated tumors." (PMID 35780223, 2022). "Activation of PIK3CA mutations in cancer predominantly leads to the dysregulation of the PI3K/AKT/mTOR pathway." (PMID 36333792, 2022). "According to The Cancer Genome Atlas and the US National Cancer Institute, PIK3CA is the second most mutated gene across several major cancer types investigated, resulting in a mutational frequency of over 12%." (PMID 35780223, 2022). "Here, PIK3CA encodes phosphatidylinositol-3-kinase, which plays an important role in activating the Akt signaling pathway, the regulator of several cancer-related activities." (PMID 36499051, 2022). "PIK3CA, which encodes the p110α catalytic subunit of PI3Kα, is mutated and overexpressed in many human cancers, and for this reason isoform-specific inhibitors have been developed as candidate therapeutics." (PMID 35873156, 2022). "Referencing previous studies, the frequency of the PIK3CA mutated gene varies from 10 to 15% in human cancers." (PMID 36539659, 2022). "PIK3CA is not only one of the PI3K/AKT/mTOR pathway members but is also the most frequently mutated oncogene in human cancers." (PMID 36333792, 2022). "Recurrent missense mutations of the PIK3CA oncogene are among the most frequent drivers of human cancers." (PMID 36353506, 2022). "PIK3CA mutations are amongst the most prevalent somatic mutations in cancer and are associated with resistance to first-line treatment along with low survival rates in a variety of malignancies." (PMID 35780223, 2022). "PIK3CA mutations appear frequently and in multiple stages of cancer; in early primary tumor formation, late in the carcinogenesis process, right before or during invasion, and during metastatic lesions." (PMID 35682652, 2022). "Together, those data suggest that p85β dissociates from the PI3K complexes and translocates into the nucleus in cancer cells with a PIK3CA helical domain mutation." (PMID 35418124, 2022). "Fifteen (11.9%) cancers harbored 16 PI3K pathway mutations: PIK3CA (n = 7), AKT2 and RICTOR (n = 3 each), PTEN, PIK3C2B, and PIK3R1 (n = 1 each)." (PMID 36124727, 2022). "Among the most commonly mutated genes in cancer is PIK3CA, which encodes the p110 alpha catalytic subunit of class 1A PI3K, and the negative pathway regulator phosphatase and tensin homolog (PTEN)." (PMID 36670929, 2022). "This review will provide an overview of the current literature on this topic and aims to analyze possible mechanisms and targets behind the aspirin sensitivity of PIK3CA-mutated cancers." (PMID 35780223, 2022). "The evidence for the effect of aspirin on deregulated metabolism in PIK3CA-mutated cancer is considerable." (PMID 35780223, 2022).
cancer (continued). "For instance, oncogenic PIK3CA mutations have been reported to reprogram metabolism in a variety of cancers including BCa." (PMID 34980012, 2022). "The APOBEC enzymes likely generate many of the driver mutations in HPV-associated cancers, being directly implicated in generating oncogenic helical domain PIK3CA mutations and, consequently, HPV-driven tumourigenesis." (PMID 34663790, 2021). "Cancer-associated mutations, including mutations in PIK3CA, are frequently found in deep infiltrating endometriosis (DIE)." (PMID 34172890, 2021). "In the context of PIK3CA mutation or amplification, high expression of FSCN1 is associated with poor prognosis and radiotherapy response in cancer patients; mutant PIK3CA (E542K and E545K) can enhance glucose metabolism and cell proliferation in cancer cells." (PMID 35069968, 2021). "PIK3CA gene is frequently dysregulated in multiple cancers, both by point mutations and amplification." (PMID 34054126, 2021). "In contrast, the relationship of these scores with PIK3CA mutation status was unexpected–cancers with one PIK3CA mutant copy showed a decrease in both scores, while they increased in cancers with additional copies." (PMID 34762647, 2021). "We recently found that PIK3CA-associated cancers often harbour multiple mutated PIK3CA copies, and demonstrated that homozygosity but not heterozygosity for PIK3CAH1047R leads to self-sustained stemness in hPSCs." (PMID 33514588, 2021). "Three hotspot mutations E542K, E545K, and H1047R underlie over 2/3 of patients with PIK3CA-associated cancers and PROS." (PMID 34074347, 2021). "Across cancer types, PIK3CA H1047 mutations show comparable frequencies between young adult and later-onset cases, while PIK3CA E545K and E542K hotspot mutations display age dependence, most notably in BRCA, CESC, COAD, and UCEC." (PMID 34788626, 2021). "A specific PIK3CA mutation in kinase domain causes higher expression of AR in cancer cells, both in cells with full SR expression and ER, PR deficient." (PMID 34638264, 2021). "A decrease in uPAR expression on the cell surface mitigates the development of hallmarks of cancer caused by PIK3CA and KRas mutations in colorectal cancer." (PMID 34729105, 2021). "PIK3R1 variants that fail to inhibit p110α activity, usually by disruption of the inter-SH2 domain, cause constitutive PI3K pathway activation, and are enriched in cancers, albeit much less commonly than PIK3CA variants." (PMID 34040190, 2021). "The PIK3CA gene was found to be mutated, on average, in 15% of human cancers, and cancers of the liver, breast, and colon harbor the most PIK3CA mutations, with average mutational frequencies of 36%, 26%, and 25%, respectively." (PMID 33572326, 2021). "PIK3CA mutations represented one of the most frequent co-alterations in HER2-mutant cancers 56; and this is a problem, as PIK3CA mutations are known to result in resistance to anti-HER2 treatment." (PMID 33570867, 2021). "Alpelisib/BYL719/Piqray is a potent oral selective PI3Kα inhibitor targeting PIK3CA-mutated cancers." (PMID 33801659, 2021). "Activating PIK3CA mutations are known ‘drivers’ of human cancer and developmental overgrowth syndromes." (PMID 33514588, 2021). "It has been well-documented that activation of the PI3Ks pathway is involved in multiple human malignancies, while the effect of PIK3CA mutations on the prognosis of patients is controversial for different human cancers." (PMID 34217313, 2021). "Gain-of-function mutations in PIK3CA have been identified in many cancers with a global incidence of 26% and an incidence of approximately 29% in Arab BCas." (PMID 33868589, 2021).